CACNA1A (calcium voltage-gated channel subunit alpha1 A)
Diseases named in the same sentence as CACNA1A in open-access papers (continued):
Sharing a sentence is not in itself a finding about the gene and the disease.
epilepsy (continued). "In the current study, we investigated reported families with epilepsy or recurrent seizures and CACNA1A pathogenic variants and then, looked for any relationship between age at onset, neurodevelopmental disorders, type of seizures, brain imaging abnormalities, genotype, and protein domains." (PMID 34727962, 2021). "Besides, only two cases in that study presented with epilepsy, thus, questioning the role of epilepsy in developing ID for the cases with CACNA1A variants." (PMID 33985586, 2021). "Previous studies have also shown the role of the CACNA1A gene in causing epilepsy." (PMID 34727962, 2021). "Indeed, CACNA1A variants have been found in the setting of severe epileptic syndromes including Ohtahara syndrome, epilepsy of infancy with migrating focal seizures and Lennox-Gastaut syndrome." (PMID 33737904, 2021). "Investigation in clinical data in patients with CACNA1A pathogenic variants and epilepsy as an only or one of the symptoms have shown that different types of seizures may occur in these patients." (PMID 34727962, 2021). "The Cacna1a and Cacna2d3 genes, which encode calcium voltage-gated channel subunit alpha1A and calcium voltage-gated channel auxiliary subunit alpha2delta3, respectively, are involved in different types of epilepsy, as described in the literature." (PMID 32168507, 2020). "Yet, it is uncertain whether her clinical course stems from the sequelae of stroke, the sequelae of refractory epilepsy, the underlying novel CACNA1A variant, or, most likely, a combination of all of these." (PMID 32692472, 2020). "Here, we present the case of a 4‐year‐old female with a history of recurrent ischemic strokes starting at 6 weeks of age, intractable epilepsy, and significant global developmental delay who was found to have a novel likely pathogenic, de novo variant in CACNA1A (p.Leu1692Gln)." (PMID 32692472, 2020). "In addition, Cacna1a S218L mice homozygous for the mutation develop multiple, spontaneous, tonic clonic seizures and die from sudden unexpected death in epilepsy (SUDEP)." (PMID 32168507, 2020). "Finally, beyond the established CACNA1A-related conditions for EA2, SCA6, and FHM1, CACNA1A variants have also been identified in patients with other phenotypes like acute striatal necrosis, hemiplegia-hemiconvulsion-epilepsy, and recurrent ischemic stroke." (PMID 32471306, 2020). "This may suggest that, although CACNA1A contributes to epilepsy mutational load, the noise from other pathway-related genes (CHRNA4, KCNQ2, KCNQ3 and PLCB1) compromises this effect." (PMID 27984588, 2016). "However, the specific mechanisms by which CACNA1A variants lead to epilepsy are not fully understood and may differ based on the mutation and its impact on channel function." (PMID 40111503, 2025). "Indeed, epilepsy is a very common symptom of CACNA1A gene variants beside FHM1/SHM1." (PMID 33425808, 2020). "A broad spectrum of seizure types has been reported in CACNA1A-related epilepsy with status epilepticus often being the initial manifestation." (PMID 40703772, 2025). "This study aims to address this gap by investigating the frequency of selected SNPs in CACNA1A, CACNA1C, and CACNA1H in Korean children with DD/ID, and by evaluating their association with epilepsy comorbidity." (PMID 40725423, 2025). "A total of nine SNPs in the CACNA1A, CACNA1C, and CACNA1H genes were selected based on their reported associations with neurodevelopmental disorders and epilepsy." (PMID 40725423, 2025). "This study aimed to investigate the association of polymorphisms in CACNA1A, CACNA1C, and CACNA1H with DD/ID and epilepsy comorbidity in Korean children." (PMID 40725423, 2025). "Pathogenic variants in CACNA1A, KCNA2 and KMT2B were associated with epilepsy; seizures are a known feature of the first two." (PMID 39048885, 2024).
epilepsy (continued). "The present case of childhood-onset CACNA1A-related epilepsy with the leading symptoms of mild generalized epilepsy, mild intellectual impairment and gait ataxia highlights the variable intrafamilial phenotypic spectrum of CACNA1A-related diseases." (PMID 39416668, 2024). "Herein, we reported the clinical characteristics of a CACNA1A cohort recruited through multiple channels (adult movement disorder clinic, epilepsy and headache outpatient clinic, pediatric clinic) at a single institution." (PMID 39110218, 2024). "As a result, our development study utilized the knockdown of the Cac gene (the ortholog of CACNA1A) to further investigate the impact of epilepsy candidate genes on development." (PMID 37152436, 2023). "For example, EA and epilepsy associations include EA1 (KCNA1), EA2 (CACNA1A), EA5 (CACNB4), EA6 (SLC1A3), SCN2A, KCNA2, ATP1A3, SLC2A1, and PRRT2." (PMID 37008993, 2023). "Based on the current literature, CACNA1A sequencing should be considered also in the settings of early epilepsy and/or developmental delay when chronic cerebellar signs or a positive family history for FHM/EA are present." (PMID 33737904, 2021). "More than 100 genes are involved in developing epilepsy phenotype, and there have been several reports of the CACNA1A gene." (PMID 34727962, 2021). "In another review, both gain- and loss-of-function variants in CACNA1A, gain-of-function variants in CACNA1H, and variants in CACNA1G were linked to epilepsy." (PMID 33985586, 2021). "Looking into the DEG subnetwork, we found that some well-known ASD candidate genes, such as Kcnma1, Shank2, Cacna1a and Cacna1b, and epilepsy candidate genes, such as Scn3a, Grin2a, Gabrg2, and Grin2b, are hub genes in this subnetwork." (PMID 32033586, 2020). "Motivated by epilepsy coincidence, the EEG has also been characterized as abnormal in patients similar to our Patient 2, with mutations in CACNA1A gene, where mixed patterns of slowing and spike and wave activity have been observed in scalp potentials." (PMID 26342528, 2016). "Our study corroborates previous reports, showing that cases harbouring CACNA1A variants typically present with ID/GDD, early-onset progressive ataxia, progressive cerebral atrophy, epilepsy, severe brain edema, coma, stroke-like presentations, and movement disorders." (PMID 41456028, 2025). "In conclusion, patients with CACNA1A-related epilepsy are prone to develop status epilepticus." (PMID 40703772, 2025). "Mutations in CACNA1A (encoding the α1A subunit of the P/Q-type calcium channel) are implicated in familial hemiplegic migraine type 1 (FHM1) and also confer susceptibility to epilepsy." (PMID 40949139, 2025). "The role of voltage-gated channels in the activity of neuronal excitability indicates that mutations in Ca2+ channel genes CACNA1A, CACNA1H, CACNA2D2, and CACNB4 might be associated with the occurrence of epilepsy." (PMID 38383918, 2024). "In addition, atypical Rett syndrome with early-onset epilepsy was associated with a de novo variant in the S6 transmembrane segment of domain III of the P/Q type calcium channel, CACNA1A (c.2128G > A, p.Ala710Thr)." (PMID 39416668, 2024). "Monogenic epilepsies can be characterized according to the gene function affected: Impaired function of ion channels (e.g., CACNA1A), receptors (e.g., GABRB3), transporters (e.g., SLC2A1), synapse-related (e.g., PRRT2), and other pathways (e.g., CDKL5, PCDH19) are associated with epilepsy." (PMID 38125836, 2023). "Similar to the geographical distribution of CACNA1A-related epilepsy, there could be a racial disparity in the distribution of CACNA1A-related GDD/ID." (PMID 37555011, 2023). "Noteworthily, CACNA1A-related epilepsy has some provoking factors including fever for most of the cases, infection, mild head trauma, stress, excitation, bathing, climatic changes, excitation, agitation, and traveling which somehow present like mitochondrial diseases." (PMID 37555011, 2023).
epilepsy (continued). "The deletion of the Cacna1a in adult mice reproduced the absence epilepsy phenotype by different thalamic bursting mechanisms suggesting that Cav2.1 channels are important for preserving standard thalamocortical oscillations as well as motor regulation in the adult brain." (PMID 37555011, 2023). "Finally, diagnostic findings in patients with syndromic vs. non-syndromic symptoms revealed a significant overlap of frequent causes of monogenic epilepsies, including SCN1A, CACNA1A, and SETD1B, confirming the heterogeneity of the associated conditions." (PMID 38125836, 2023). "Although it remains to be determined if SOM cell inhibitory synapses demonstrate learning-induced changes, mTORC1-dependent axonal sprouting by CA1 SOM cells takes place in the CACNA1A mouse model of epilepsy which is characterized by impaired synaptic inhibition by Pvalb interneurons." (PMID 35521524, 2022). "After searching in DrugBank, we retrieved a total of 47 anti-epileptic drugs and 151 targets, of which identified 17 target genes (CACNA1A, CHRNA4,CHRNA7,GABRA1,GABRA2,GABRB2,GABRG2,GRIK1,GRIN1,GRIN2B,KCNQ2,KCNQ3,SCN1A,SCN2A, SCN3A,SCN8A and SCN9A) were overlapped with risk genes of epilepsy." (PMID 36006933, 2022). "Mutations in STRADA, SYNJ1, CACNA1A and NPRL3 have also been reported with severe epilepsy-related disease, but the association has not been reported for heterozygous variants in isolated forms of epilepsy." (PMID 36539902, 2022). "Epilepsy has been variably reported in patients with CACNA1A-related disease." (PMID 32471306, 2020). "The CACNA1A loss-of-function (LOF) mutations induce the synaptic dysfunction of cortical interneurons and specifically reduce or impair the function of cortical GABA neurotransmitters, resulting in the occurrence of EA2 and epilepsy." (PMID 33425808, 2020). "In addition, a small cluster of the network showed co-expression of several genes (NRXN1, CACNA1A, CDH10, and others) associated with autism and/or epilepsy." (PMID 27358653, 2016). "Disruption in CACNA1A’s communication within the extensive calcium equilibrium network may lead to neural electrophysiological perturbations, contributing to conductivity-related pathologies like seizures and epilepsy." (PMID 38689878, 2024). "However, a recent study reported a de novo CACNA1A mutation causing hemiplegic migraine and developmental delay but without epilepsy, revealing a loss-of-function of Cav2.1 channel." (PMID 34384358, 2021). "Interestingly, de novo CACNA1A mutations have been recently associated with a sporadic early infantile epileptic encephalopathy (the so-called EIEE42) resulting in a severe clinical phenotype with developmental delay and epilepsy." (PMID 33544220, 2021). "The CACNA1A gain-of-function (GOF) mutations could enhance the neuronal excitability by increasing the influx of calcium ions and release of glutamate, decreasing the threshold of CSD, resulting in the occurrence of HM and epilepsy." (PMID 33425808, 2020). "This study focused specifically on three voltage-gated calcium channel genes—CACNA1A, CACNA1C, and CACNA1H—due to their well-established roles in neurodevelopmental disorders and epilepsy." (PMID 40725423, 2025). "However, the relationship between CACNA1A and epilepsies has not been defined and it is unknown the genotype-phenotype correlation in the spectrum of CACNA1A-associated disorders." (PMID 35600082, 2022). "Several other genes that we have identified as undergoing mTLE-linked alternative splicing events also have been associated with other, non-mTLE forms of human epilepsy, including CACNA1A, CACNA1H, CLCN2, and GABRG2, indicating that these also may be of particular interest in the epilepsy field." (PMID 17343748, 2007). "Currently, genotype–phenotype correlations of the CACNA1A – related neurodevelopmental disorders such as GDD/ID, ASD, and epilepsy are unknown." (PMID 37555011, 2023). "CACNA1A is related to a wide range of phenotypes including GDD/ID, epilepsy, and ASD." (PMID 37555011, 2023).
epilepsy (continued). "The larger CACNA1G p-value (6.56 × 10−5) when compared to hsa04930 p-value (1.2 × 10−6) suggests that the other two genes CACNA1A and/or SLC2A2 may contribute to epilepsy with small effect sizes." (PMID 27984588, 2016).
familial hemiplegic migraine type 1 (90 papers, 2010 to 2025). "There is a genetic basis for certain migraines, including hemiplegic migraine, which include mutations in genes like CACNA1A (calcium channel), ATP1A2 (Na/K-ATPase), and SCN1A (sodium channel)." (PMID 40149800, 2025). "Here, we focus on CACNA1A mutations underlying Familial Hemiplegic Migraine type-1 (FHM-1), a rare autosomal condition with phenotypes ranging from migraine with aura to hemiparesis and progressive cerebellar ataxia." (PMID 39568055, 2024). "Of the reported patients with hemiplegic migraine with CACNA1A mutations, 42.4% presented with encephalopathy." (PMID 37576133, 2023). "Another study focused on hemiplegic migraine and found that patients with mutations in CACNA1A, ATP1A2, or SCN1A tended to have a lower age at disease onset." (PMID 37305749, 2023). "In this case report, we highlight the adverse effects of ECT in a patient with autism spectrum disorder that was subsequently found to have a de novo pathogenic CACNA1a variant that is known to be associated with hemiplegic migraines." (PMID 36494636, 2022). "Familial hemiplegic migraine-causing mutations in CACNA1A are usually missense, and electrophysiological studies show gain-of-function (GOF) effects leading to channel hyperactivity." (PMID 35928792, 2022). "Mutations in the CACNA1A gene (which encodes CaV2.1) have been identified in patients with other forms of craniofacial pain, including familial hemiplegic migraine type 1 (FHM-1)." (PMID 33413531, 2021). "This is also evident from Cav2.1 (CACNA1A) gain-of-function mutations associated with familial hemiplegic migraine type-1." (PMID 33380256, 2021). "Here, we studied the CACNA1A p.Y1384C mutation found in two individuals with congenital ataxia, early onset cerebellar atrophy, sporadic hemiplegic migraine and intellectual disability." (PMID 33557884, 2021). "We described a large family with CACNA1A-p.Thr501Met mutation whose prevalent clinical expression was hemiplegic migraine." (PMID 34320921, 2021). "Hemiplegic migraine is a rare monogenic MA subtype caused by mutations in three main genes - CACNA1A, ATP1A2 and SCN1A - which encode ion channel and transport proteins." (PMID 31226929, 2019). "Here, we describe the first case of familial hemiplegic migraine type 1 (FHM1) resulting from a T666M mutation in the CACNA1A gene of a Chinese individual." (PMID 31824404, 2019). "Gain-of-function mutations in the human CaV2.1 gene CACNA1A cause familial hemiplegic migraine type 1 (FHM1)." (PMID 30080864, 2018). "Transgenic mice carrying the R192Q missense mutation in the Cacna1a gene, which in patients causes familial hemiplegic migraine type 1 (FHM1), exhibit increased propensity to CSD." (PMID 25877011, 2015). "This was demonstrated by studies performed in transgenic mice with familial hemiplegic migraine type 1 (FHM1) mutations of the CACNA1A gene encoding for CaV2.1." (PMID 24179464, 2013). "Up to now, four causative genes have been described in hemiplegic migraine (HM): CACNA1A on chromosome 19p13 (FHM1, MIM #301011), ATP1A2 at 1q23 (FHM2, MIM #182340), SCN1A at 2q24 (FHM3, MIM #182389) and, recently, PRRT2 at 16p11.2 (MIM #614386)." (PMID 24498617, 2013). "Familial hemiplegic migraine type 1 is a form of migraine with aura and reversible hemiparesis also caused by missense nucleotide mutations in the CACNA1A gene that alter channel gating and enhance the channel activity at negative potentials." (PMID 22379397, 2011). "The R192Q mutation of the CACNA1A gene, encoding for the α1 subunit of voltage-gated P/Q Ca2+ channels (Cav2.1), is associated with familial hemiplegic migraine-1." (PMID 20735819, 2010). "In addition to EA2, CACNA1A mutations can result in two other autosomal dominant disorders: familial hemiplegic migraine type 1 (FHM1) and spinocerebellar ataxia type 6 (SCA6)." (PMID 37008993, 2023).
familial hemiplegic migraine type 1 (continued). "Likewise, alternative splicing in the C-terminal tail of Cav2.1 α1-subunits of P/Q-type channels (CACNA1A) affected the functional changes of several gain-of-function missense mutations causing Familial Hemiplegic Migraine Type 1, including S218L." (PMID 30465465, 2018). "The present study investigated the role of calcium/calmodulin-dependent serine protein kinase (CASK) in controlling P2X3 receptor expression and function in trigeminal ganglia from Cacna1a R192Q-mutated knock-in (KI) mice, a genetic model for familial hemiplegic migraine type-1." (PMID 24294842, 2013). "Familial hemiplegic migraine 1 (FHM1) is in the majority of cases caused by a missense mutation of the CACNA1A gene that codes for the pore-forming subunit of the neuronal voltage-gated calcium channel Cav2.1, leading to gain-of-function effects that result in hyperexcitability." (PMID 35655042, 2022). "Mutations in CACNA1A, ATP1A2, and SCN1A, responsible for familial hemiplegic migraine types 1, 2, and 3 (FHM1, FHM2, and FHM3), are also linked to epilepsy." (PMID 40149800, 2025). "We provide single-patient data supporting the evaluation of anti-CGRP antibodies as alternative strategy in CACNA1A-related therapy refractory hemiplegic migraine." (PMID 39110218, 2024). "Studies on hemiplegic migraine also suggest its relevance to the SCA6-responsible gene CACNA1A, which encodes a subunit of P/Q type voltage-gated calcium channel (Cav2.1)." (PMID 35326323, 2022). "The EA2 clinical picture is complicated by the possible overlap with other two autosomal dominant (AD) CACNA1A allelic disorders: Familial Hemiplegic Migraine type 1 (FHM1) and Spinocerebellar Ataxia type 6 (SCA6)." (PMID 32899446, 2020). "Mutations of the CACNA1A gene, coding for the alpha subunit of Cav 2.1 channels, are the cause of two other allelic disorders, Spinocerebellar ataxia 6 (SCA6) and Familial Hemiplegic Migraine 1 (FHM1)." (PMID 32899446, 2020). "Sporadic hemiplegic migraine: two patients showed a deletion in exons 41–43, while the rest of HM patients showed a deletion in the terminal part of the CACNA1A gene (ex 47)." (PMID 30167989, 2018). "Dominant mutations in CACNA1A underlie at least three allelic diseases: EA2, familial hemiplegic migraine type 1 and spinocerebellar ataxia type 6." (PMID 22379397, 2011). "Mutations in the CACNA1A gene have been found to be responsible for three disorders with autosomal dominant inheritance: i) Episodic Ataxia 2 (EA2; MIM: 108500), ii) familial hemiplegic migraine type 1 (FHM1; MIM: 141500), and iii) spinocerebellar ataxia type 6 (SCA6; MIM: 183086)." (PMID 30167989, 2018). "In addition to EA2, mutations in CACNA1A are responsible for two other allelic disorders: familial hemiplegic migraine type 1 (FHM1) and spinocerebellar ataxia type 6 (SCA6)." (PMID 27066515, 2016). "Although hemiplegic migraine (HM) is linked to CACNA1A mutations that enhance CaV2.1 channel activity and EA2, on the contrary, is associated to loss-of-function mutations, symptomatology overlap of HM, EA2 and SCA6 are well recognized at the clinical level." (PMID 26716990, 2015). "In common with AHC, episodic hemiplegia or hemiparesis is a clinical feature of familial hemiplegic migraine type 1 (FHM1), an autosomal dominant disorder caused by missense mutations in the CACNA1A gene encoding the pore-forming α1A-subunit of neuronal, voltage-gated CaV2.1 calcium channels." (PMID 23527305, 2013). "CACNA1A‐related disease phenotypes described more recently have revealed that there is a wide phenotypic overlap between hemiplegic migraine, diverse forms of cerebellar dysfunction and epilepsy, and that genotype–phenotype correlation might be not as strict as initially reported." (PMID 33816657, 2021).